NQO1 (NAD(P)H quinone dehydrogenase 1)
Diseases named in the same sentence as NQO1 in open-access papers (continued):
Sharing a sentence is not in itself a finding about the gene and the disease.
cervical carcinoma (15 papers, 2014 to 2025). A carcinoma arising from either the exocervical squamous epithelium or the endocervical glandular epithelium. "In breast, colorectal, ovarian and cervical cancer types, elevated expression of NQO1 is closely associated with poor prognosis 3-5." (PMID 36793872, 2023). "NQO1 overexpression was reported to be associated with high tumor grade in carcinoma of cervix and breast, with advanced stage cervical, breast, colon and liver carcinomas and with nodal metastases." (PMID 28983331, 2015). "As regarding cervical carcinoma, a significant association between increased NQO1 mean expression and tumor grade (P = 0.045) was detected." (PMID 28983331, 2015). "Hu’ results indicated that functional polymorphisms in NQO1 SNP609 associate with the risk of cervical cancer especially in women infected with type 16- and/or type 18-related HPVs." (PMID 24912939, 2014). "To determine the role of the Nrf2/Keap1 signaling cascade in cepharanthine-induced oxidative stress, we analyzed the protein expression patterns of Nrf2, Keap1, NQO1, and HO-1 in cepharanthine-treated cervical cancer cells using Western blot analysis." (PMID 41300481, 2025). "In this study, we show that osthole induces apoptosis and GSDME-mediated pyroptosis by increasing generation of ROS through inhibiting NQO1, thereby inhibiting the proliferation of cervical cancer cells." (PMID 35720178, 2022). "At the same time, several studies reported arelationship between NQO1 609TT genotypes and the riskof cervical cancer." (PMID 35342856, 2022). "It has reported that osthole inhibited the NQO1 expression to overcome cisplatin resistance in cervical cancer SiHa and CaSki cells." (PMID 35720178, 2022). "Breast and cervical cancer patients with high-level NQO1 expression are also correlated with lower disease-free survival and 5-year overall survival rates compared with those with low-level NQO1 expression." (PMID 31909204, 2020). "The NQO1 protein showed a mainly cytoplasmic staining pattern in cervical cancer cells, and only three cases of cervical SCC showed a nuclear staining pattern." (PMID 24912939, 2014). "In addition, upregulation of NQO1 is closely correlated with poor prognosis in breast, colorectal, ovarian, and cervical cancers 3-5." (PMID 36793872, 2023). "Interestingly, the strongly positive rate of NQO1 protein was slightly higher in well-differentiated SCC (43.75%) than in CIN3 (40.74%) (P > 0.05), indicating that abnormal NQO1 expression might be an early event in the progression of cervical cancer." (PMID 24912939, 2014). "β-lapachone significantly inhibited the proliferation and metastasis of cervical cancer cells by regulating glucose metabolism, reducing tumor angiogenesis, and suppressing epithelial-mesenchymal transition (EMT) in cells with high NQO1 expression." (PMID 40051559, 2025). "We found increased NQO1 expression from normal tissue to SIL and cervical carcinoma and then from SIL to carcinoma." (PMID 28983331, 2015). "In fact, studies have shown that higher levels of NAD(P)H quinone dehydrogenase 1 (NQO1) and NRF2 expression are associated with higher-grade cancers such as endometrial and cervical carcinomas as opposed to healthy tissue and precancerous lesions." (PMID 37927596, 2023).
cervical carcinoma (continued). "To date, the correlation between NQO1 expression and cervical cancer has not been adequately studied." (PMID 24912939, 2014). "Similarly, compared with normal cervical epithelia, the strongly positive rate of NQO1 protein expression was also significantly higher in cervical SCC and intraepithelial neoplasia tissues, indicating that NQO1 expression might be related to tumorigenesis of cervical cancer." (PMID 25880877, 2015).
pulmonary fibrosis (15 papers, 2016 to 2025). Chronic progressive interstitial lung disorder characterized by the replacement of the lung tissue by connective tissue, leading to progressive dyspnea, respiratory failure, or right heart failure. "We found BLM-induced lung fibrosis were more severe in Nrf2−/− mice compared to WT mice with reduced expressions of HO-1 and NQO1." (PMID 29362432, 2018). "Furthermore, Nrf2-mediated upregulation of downstream targets HO-1 and NQO1 has been shown to suppress EMT-driven pulmonary fibrosis." (PMID 40520173, 2025). "The results showed that bergenin reduced the levels of ROS and MDA and increased the levels of GSH, the activity of SOD, and the expression levels of HO-1 and NQO1, suggesting that the anti-pulmonary fibrosis effect of bergenin is related to its antioxidant effect." (PMID 35204190, 2022). "In a mouse pulmonary fibrosis model, CHE increased the expression of Nrf2, HO-1, and NQO1, and alleviated pulmonary fibrosis by activating the Nrf2/ARE pathway." (PMID 41008971, 2025). "In addition, in a previous study, it was found that intracellular iron metabolism could be regulated by up-regulating the expression levels of Nrf2, HO-1, and NQO1, preventing iron overaccumulation and lipid peroxidation, and thus, alleviating radiation-induced pulmonary fibrosis." (PMID 40137129, 2025). "The activation of Nrf2 can increase the level of glutathione-S-transferase (GST), NADP(H): quinone oxidoreductase 1 (NQO1), thioredoxin, glutathione peroxidase (GPx), and other antioxidant enzymes, thereby decreasing ROS and reducing pulmonary fibrosis." (PMID 33532135, 2021). "Research in bleomycin-induced pulmonary fibrosis rats has suggested the protective effects of NRF2 signaling pathways, including NQO1 and HO1, on oxidative damage, attenuating pulmonary fibrosis." (PMID 28785522, 2017). "Nrf2 induces the expression of antioxidant genes including glutathione S-transferase (GST), NAD(P)H: quinone oxidoreductase 1 (NQO1), Hemeoxygenase1 (HO1), and ferritin heavy chain 1 (FTH1), which have been shown to protect against pulmonary fibrosis in murine models." (PMID 37875506, 2023). "Reduced the levels of caspase-3, IL-1β, TNF-α, TGF-β, HYP, 3-NT, and 4-HNE; increased the levels of Nrf2, HO−1, NQO1, SOD1, and CAT; alleviated BLM-induced alveolar epithelial cell apoptosis, alveolitis, collagen accumulation, lung oxidative stress, and lung fibrosis." (PMID 36139759, 2022).
Cerebral ischemia (14 papers, 2013 to 2025). Restriction of arterial blood supply to the brain associated with insufficient oxygenation to support the metabolic requirements of the tissue. "A study of cerebral ischemia discovered that chlorogenic acid modulated the Nrf2 pathway and enhanced the expression of Nrf2, HO-1, and NQO-1 to counteract the reperfusion-induced brain injury that caused brain ischemia." (PMID 36686668, 2022). "In BV2 cells after cerebral ischemia reperfusion, Nrf2 ROS response was linked to Nqo1 expression." (PMID 33260800, 2020). "Some studies confirmed that heme oxygenase-1 (HO-1) and NAD(P)H quinone oxidoreductase 1 (NQO1) expression increased after cerebral ischemia." (PMID 36552584, 2022). "A Western blot analysis demonstrated the upregulation of nuclear factor erythroid 2–related factor 2 (Nrf2), heme oxygenase-1 (HO-1), and NAD(P)H:quinone oxidoreductase 1 (NQO1) and the downregulation of Kelch-like, ECH-associated protein 1 (Keap1) in the cerebral ischemia–reperfusion model." (PMID 40283984, 2025). "In a rat model of cerebral ischemia, the inhibition of mitochondrial dihydrolipoamide dehydrogenase, a potential target for protection against ischemic insults, resulted in the upregulation of NQO1 expression." (PMID 38167027, 2024). "To verify whether curcumin inhibited oxidative stress and induced the expression of NQO1 after focal cerebral ischemia/reperfusion injury in rats via PI3K/Akt pathway involving Nrf2, we performed a PI3K/Akt inhibition study with LY294002." (PMID 23555802, 2013).
cholangiocarcinoma (14 papers, 2014 to 2025). A carcinoma that arises from the intrahepatic biliary tree (intrahepatic cholangiocarcinoma) or from the junction, or adjacent to the junction, of the right and left hepatic ducts (hilar cholangiocarcinoma). "On the contrary, loss of NQO1 expression appeared to be candidates for adjuvant chemotherapy in patients with cholangiocarcinoma." (PMID 28983331, 2015). "In cholangiocarcinoma cells, scopoletin and umbelliferone showed a strong inhibitory effect on NQO1, and scopoletin also showed strong cytotoxicity on cholangiocarcinoma cells." (PMID 33344242, 2020). "Moreover, the activity of NAD(P)H:quinone oxidoreductase-1 (NQO1), a xenobiotic-metabolizing and antioxidant enzyme, is suppressed by inflammatory cytokines in cholangiocarcinoma cells, with the consequent increase in NO production and oxidative stress." (PMID 38247453, 2023). "Moreover, NQO1 was found to be expressed at high levels in many human cancers, including liver, colon, pancreas and cholangiocarcinoma." (PMID 25880877, 2015). "In order to explore whether NQO1 was involved in the cytotoxicity of scopoletin to cholangiocarcinoma cells, Khunluck also tested the cytotoxicity of scopoletin to cholangiocarcinoma cells that had been introduced with NQO1 siRNA and found that the cytotoxicity was reduced." (PMID 33344242, 2020). "It is important to note that several types of solid tumors, such as cholangiocarcinoma, lung, pancreas, breast and squamous cell carcinoma of the uterine cervix, have high expression of NQO1, and there are studies that demonstrate a β-lapachone preferential tropism for NQO1-positive cells." (PMID 32085381, 2020). "Currently, NQO1-mediated chemotherapy resistance has been confirmed in cholangiocarcinoma tumor cells, and the targeted metabolism drug KP372-1 mediated by NQO1 has effectively inhibited tumor growth in xenograft models." (PMID 35501667, 2022).
bladder cancer (13 papers, 2001 to 2026). "Numerous studies have been performed to investigate the association between NQO1 Pro187Ser polymorphism and bladder cancer risk; nevertheless, the results remain controversial." (PMID 25602258, 2015). "In other words, low penetrance polymorphism, like NQO1 Pro187Ser, commonly only has weak effect on bladder cancer risk." (PMID 25602258, 2015). "False-positive report probability values for associations between bladder cancer risk and the frequency of genotypes of NQO1 gene." (PMID 25602258, 2015). "As expected, it has been reported that the polymorphism in the xenobiotic metabolizing enzyme gene, NQO1 Pro187Ser, is associated with bladder cancer risk." (PMID 25602258, 2015). "In the current updated meta-analysis of 15 studies including a total of 4298 cases and 4275 controls, we found that the NQO1 Pro187Ser polymorphism was associated with increased bladder cancer susceptibility." (PMID 25602258, 2015). "Characteristics of studies included in the meta-analysis for an association between NQO1 Pro187Ser (1800566 C>T) polymorphism and bladder cancers risk." (PMID 25602258, 2015). "Meta-analysis of the association between NQO1 Pro187Ser (1800566 C>T) polymorphism and bladder cancer risk." (PMID 25602258, 2015). "A total of 39 publications examining the association between NQO1 Pro187Ser and bladder cancer risk were identified from MEDLINE and EMBASE, and two additional publications from CBM." (PMID 25602258, 2015). "Many molecular epidemiology studies have investigated the association between NQO1 Pro187Ser polymorphism and bladder cancer risk, but the conclusions were controversial." (PMID 25602258, 2015). "Mutations in DNA repair genes (XRCC3) and variants in genes coding for xenobiotic-transforming enzymes (NAT2, GSTM1, GSTP1 and NQO1) have been shown to modify the susceptibility to bladder cancer." (PMID 19755987, 2009). "Despite some limitations, our meta-analysis provides sufficient evidence that NQO1 Pro187Ser polymorphism may contribute to bladder cancer risk." (PMID 25602258, 2015). "Relatively greater FPRP values were found for other noteworthy findings between NQO1 Pro187Ser polymorphism and bladder cancer risk may be due to the limited sample sizes, which need further validation in the studies with large sample size." (PMID 25602258, 2015). "In conclusion, the current meta-analysis indicates that the NQO1 Pro187Ser polymorphism may confer host increased genetic susceptibility to the risk of bladder cancer." (PMID 25602258, 2015). "Overall, the NQO1 187Ser carriers were associated with an increased bladder cancer risk (homozygous: OR = 1.43, 95% CI = 1.08-1.90; recessive: OR = 1.33, 95% CI = 1.03-1.72; dominant: OR = 1.19, 95% CI = 1.04-1.37, and allele comparing: OR = 1.18, 95% CI = 1.06-1.33)." (PMID 25602258, 2015). "Besides this study, numerous studies have investigated the association between NQO1 Pro187Ser polymorphism and bladder cancer risk, however, the conclusions remain controversial rather than conclusive." (PMID 25602258, 2015). "Of these, NQO1, CCL2, and MDM2 are associated with increased risk or tumor promoting function in bladder cancer." (PMID 28122346, 2017). "Currently, there are several genetic polymorphisms which have been identified as risk factors of bladder cancer, such as cyclin D1 (CCND1) G870A polymorphism and NQO1 C609T polymorphism." (PMID 24390660, 2014). "Similarly, WFA upregulates the mRNA expression of antioxidant genes (NFE2L2, CAT, SOD1, TXN, GSR, NQO1, and HMOX1) in bladder cancer cells associated with oxidative stress generation." (PMID 34209212, 2021). "For instance, we observed significantly increased risk of developing bladder cancer among never smokers who carried variant alleles of NQO1 Pro187Ser polymorphism." (PMID 25602258, 2015).
bladder cancer (continued). "The shapes of the funnel plots seemed symmetrical, indicating no significantly statistical evidence of publication bias for the association between NQO1 Pro187Ser polymorphism and bladder cancer risk (data not shown)." (PMID 25602258, 2015). "In the current study, we found that the NQO1 Pro187Ser polymorphism was shown to associate with bladder cancer in hospital-based subgroups but not population-based subgroups." (PMID 25602258, 2015). "A urinary bladder cancer study found GCLC, GCLM, HMOX1, and NQO1 to be upregulated." (PMID 41109135, 2025). "The expression levels of p62, p-Nrf2 and NQO1 was upregulated and reached its peak level at 12 h in C-2-treated bladder cancer cells, and the expression of Nrf2 and Keap1 has no obviously changes." (PMID 31685029, 2019).
Cognitive impairment (11 papers, 2019 to 2026). Abnormal cognition is characterized by deficits in thinking, reasoning, or remembering. "It has been reported that Nrf2 increases the transcription of heme oxygenase-1 (HO-1) and NAD(P)H: quinone oxidoreductase 1 (NQO1) that mitigates the oxidative stress and inflammation of the brain and eventually improves the cognitive impairment in T2DM." (PMID 36247985, 2022). "Overall, our study illustrated that AS-IV decreases the fasting blood glucose levels, alleviates oxidative stress and neuroinflammation, and ultimately improves cognitive impairment probably via Nrf2/Keap1/HO-1/NQO1 pathway in T2DM mice." (PMID 36247985, 2022). "Therefore, in the present study, we explored the hypothesis that AS-IV might improve diabetes-related cognitive impairment in T2DM mice by modulating the Nrf2/Keap1/HO-1/NQO1 pathway." (PMID 36247985, 2022). "The results demonstrated that broccoli intervention significantly ameliorated cognitive deficits in epileptic mice, decreased hippocampal MDA levels while enhancing antioxidant enzyme activities, and upregulated the expression of HO‐1, NQO1, and Nrf2." (PMID 40061295, 2025). "Taken together, these data suggested that AS-IV ameliorates cognitive impairment in T2DM mice by attenuating oxidative stress and neuroinflammation, possibly through modulating the Nrf2/Keap1/HO1/NQO1 pathway." (PMID 36247985, 2022).
Hypertension (10 papers, 2013 to 2024). The presence of chronic increased pressure in the systemic arterial system. "NQO1 acts both as a quinone reductase and a superoxide reductase, which protects against endothelial inflammation and spontaneous hypertension." (PMID 38231044, 2024). "Hypertension stimulation reduces the nuclear accumulation of Nrf2 and lead to down-regulation of a cluster of antioxidant genes including HO-1, NQO-1 and GSH-PX, which breaks the kidney redox balance and aggravates renal damage." (PMID 34773993, 2021). "Taken together, indoxyl sulfate, as well as hypertension, suppresses Nrf2 expression in the kidney, followed by decreased expression of HO-1 and NQO1 and increased level of 8-OHdG." (PMID 23496811, 2013). "NQO1 expression is stimulated by the oxidative stress agonist tBHQ, and the toxin dioxin (TCDD) that also induces CH and hypertension in the heart." (PMID 31598705, 2019).
ischemic stroke (10 papers, 2018 to 2025). A stroke disorder caused by obstruction of blood flow to the brain, due to thrombotic (local blood clot formation) or embolic (due to a blood clot or other material traveling from another site) event. "Growing evidence suggests a potential association between NQO1 and the pathogenesis of various cerebrovascular diseases, including ischemic stroke and cerebral infarction." (PMID 38167027, 2024). "A study on 141 patients with ischemic stroke and 139 matched control subjects has shown a significant association between NQO1 gene polymorphisms and the incidence of ischemic stroke." (PMID 38167027, 2024). "A recent investigation in individuals with ischemic stroke caused by large-artery atherosclerosis discovered that Nqo1*2 polymorphisms were associated with a decreased risk of atherosclerosis-related stroke." (PMID 35739970, 2022). "This investigation revealed a correlation between the cc genotype of NQO1 rs1800566 and the occurrence of ischemic stroke." (PMID 38167027, 2024). "In conclusion, this study demonstrated that PCGE was effective in reducing neurotoxicity in ischemic stroke associated with decreasing H2O2-induced LDH release, upregulating HO-1, NQO-1, and BDNF expressions through activation of Nrf2 in brain cells." (PMID 29765502, 2018). "Furthermore, another study showed that DLD inhibition reduces ischemic stroke damage through reduced oxidative stress, reduced cell death, increased Nrf2 signaling, and increased NQO1 activity." (PMID 37228705, 2023). "Meanwhile, we found that Ginseng pretreatment significantly enhanced expression levels of Nrf2 downstream cytoprotective and antioxidative proteins including NQO1, HO1, SOD2 and GPx1 at the early stage of ischemic stroke onset in WT, and this was completely abolished in the Nrf2−/− mice." (PMID 29628876, 2018). "Thus, to confirm the functional importance of Nrf2 activation in Ginseng’ neuroprotection, Nrf2 downstream target markers including NQO1, HO1, SOD2 and GPx in peri-infarct tissue of cortex were measured at earlier-stage of ischemic stroke onset." (PMID 29628876, 2018). "Thus, it would be worth assessing whether NQO1 and GCLC are induced in MG after ischemic stroke and determining their effects on modulating ischemic brain injury." (PMID 39469715, 2024).